THBS1 (thrombospondin 1)
Diseases named in the same sentence as THBS1 in open-access papers (continued):
Sharing a sentence is not in itself a finding about the gene and the disease.
coronary artery disease (6 papers, 2011 to 2024). "However, the LD analysis identifies a well studied gene THBS1 (thrombospondin-1), which is centromeric to gene FSIP1 and has been confirmed to increase the risk of coronary artery disease in many studies." (PMID 21569557, 2011). "In addition, CP has been confirmed to have a positive effect on diabetic complications, such as protecting diabetic atherosclerosis by inhibiting the expression of Thrombospondin-1, improving diabetic nephropathy and coronary heart disease through antioxidant and anti-inflammation effects." (PMID 38474436, 2024).
diabetic nephropathy (6 papers, 2013 to 2024). "Accumulating evidence suggests that thrombospondin 1 (TSP1) is an important player in diabetic nephropathy." (PMID 27196103, 2016). "For different renal diseases like experimental glomerulonephritis and diabetic nephropathy in rodents, we could show that thrombospondin-1 TSP-1 is the major activator of TGF-β." (PMID 24376766, 2013). "The blockade of THBS1-dependent TGF-β activity has been discovered to reduce proteinuria and improve markers of tubulointerstitial injury (fibronectin) in a murine model of diabetic nephropathy." (PMID 29950996, 2018).
hypertrophic cardiomyopathy (6 papers, 2019 to 2025). A condition in which the myocardium is hypertrophied without an obvious cause. "Proteomic profiling identified a set of six proteins with predictive value for SCD in patients with hypertrophic cardiomyopathy (HCM): thrombospondin-1 (THBS1), complement C3 (C3), aldolase A (ALDOA), Ras suppressor protein 1 (RSU1), glutathione S-transferase omega 1 (GSTO1), and talin-1 (TLN1)." (PMID 40725061, 2025).
liver cancer (6 papers, 2016 to 2024). An epithelial or non-epithelial malignant neoplasm that arises from the liver. "In addition, tissue development in patients with liver cancer has been attributed to the high expression of THBS1, which promotes angiogenesis." (PMID 36421816, 2022). "By noninvasive imaging the gene expression of THBS1 was upregulated in liver cancer." (PMID 28025641, 2016). "In VC of liver cancer, actin-related protein 2/3 (ARP2/3) and thrombospondin 1 (THBS1) are important in inducing cancer cells motility." (PMID 38737903, 2024).
liver diseases (6 papers, 2017 to 2025). "Besides its role as an attenuator of liver regeneration, THBS1 is seemingly involved in the pathogenesis of various liver diseases." (PMID 38534373, 2024).
malaria (6 papers, 2018 to 2023). Malaria is a serious and sometimes fatal disease caused by a parasite that commonly infects a certain type of mosquito which feeds on humans. "In our transcriptomic data, we also noted upregulation of two other malaria-associated cell adhesion molecules, thrombospondin-1 (THBS1) (Padj < 10−7; log2FC = 0.23 ± 0.04; linear model) and intercellular adhesion molecule-1 (ICAM1) (Padj < 10−4; log2FC = 0.30 ± 0.07; linear model)." (PMID 33563839, 2021). "Malaria disease was the single KEGG pathway identified and this was linked to IL6, syndecan-2 (SDC2) and thrombospondin-1 (THBS1) DEGS that were enriched in the down-regulated gene set." (PMID 31792230, 2019). "Within the malaria pathway, miR-193b promotes the THBS1, THBS2, and TGFβ2 genes; and regulates apoptosis by targeting myeloid leukaemia cell differentiation protein 1, among others." (PMID 29747626, 2018). "THBS1 is a multifunctional cell surface molecule with roles in platelet activation and cell-matrix interactions via interaction with metalloproteases, integrins, and ECM proteins and has been associated with cytoadherence phenotypes in severe malaria." (PMID 33563839, 2021). "Additionally, malaria pathogenicity genes (thrombospondin 1-(THBS 1), interleukin 6 (IL6), and arginine decarboxylase 2 (ADC2)) were down-regulated." (PMID 31792230, 2019). "Six genes (TGFB1, CD36, THBS1, FABP1, PCK1, and IRS1) were involved with malaria, PPAR signaling, and the adipocytokine signaling pathway." (PMID 36193307, 2022). "Among them, malaria, PPAR signaling, and the adipocytokine signaling pathway reached statistical significance (FDR value of <1 and p < 0.05) and included TGFB1, CD36, THBS1, FABP1, PCK1, and IRS1." (PMID 36193307, 2022).
malignant glioma (6 papers, 2015 to 2023). A grade III or grade IV glioma arising from the central nervous system. "Similarly, other reports found a significant association between THBS1 methylation and the survival time of patients with penile squamous cell carcinoma and malignant glioma." (PMID 26550574, 2015). "The interaction between THBS1 and SDC1 expressed in malignant gliomas promotes tumor cell invasion." (PMID 37905960, 2023).
Sjögren’s syndrome (6 papers, 2013 to 2025). "In contrast, one study using thrombospondin-1-deficient mice, an aqueous-deficient dry-eye model of Sjögren’s syndrome, found that CGRP levels were substantially reduced but the SP level remained unchanged in the cornea." (PMID 34575359, 2021). "In this study, we developed a primary culture of mouse goblet cells from conjunctival tissue and evaluated the effects on their function by inflammatory cytokines detected in the conjunctiva of mouse model of Sjögren's syndrome (Thrombospondin-1 deficient mice)." (PMID 24453426, 2013). "Additionally, the knockout of THBS1 in a murine model of dry eye disease (Sjögren’s syndrome) led to elevated levels of Th17 cells in the lacrimal gland, exacerbating inflammation." (PMID 40001591, 2025). "To mitigate potential influences, we used AAV-mediated sclera THBS1 knockout instead of THBS1 global knockout mice, as THBS1 global knockout mice develop severe dry eye, akin to autoimmune disease Sjogren’s syndrome, which may not be suitable for studying myopia models." (PMID 38355399, 2024).
aneurysm (5 papers, 2021 to 2023). Bulging or ballooning in an area of an artery secondary to arterial wall weakening. "The study found upregulated genes (including WDR43 and THBS1) and one downregulated gene associated with aneurysm rupture." (PMID 37122373, 2023). "In particular, both ACE, which is a positive modulator of Angiotensin II signaling, and Thbs1, a multifunctional protein with both pro-inflammatory and cell signaling regulatory functions, have been shown to be upregulated in aneurysm tissue and implicated in its pathogenesis." (PMID 35463747, 2022). "While our study identified 11 upregulated genes, including WDR43 and THBS1, and one downregulated gene associated with aneurysm rupture, we acknowledge the limitations of not conducting relevant experiments on miRNA." (PMID 37122373, 2023). "Among them, six hub genes might be the core genes for the rupture of aneurysms, including APP, JUN, GSK3B,ErbB2, PPBP and THBS1." (PMID 35432454, 2022). "However, in a modified AAA mouse model induced by CaCl2, a lack of thrombospondin-1 was shown to inhibit aneurysm formation by elevating tissue inhibitor of metalloproteinases-1 (TIMP1) expression but without affecting MMP expression." (PMID 34646388, 2021).
angiosarcoma (5 papers, 2012 to 2024). A malignant tumor arising from the endothelial cells of the blood vessels. "The overexpression of the miR-17-92 cluster in MYC-amplified angiosarcomas was associated with the downregulation of thrombospondin-1 (THBS1), a glycoprotein that inhibits angiogenesis." (PMID 39594601, 2024). "Since MYC-amplified angiosarcoma is associated with lower expression of thrombospondin-1 (THBS1), MYC amplification may be important in the angiogenic phenotype of angiosarcoma through upregulation of the miR-17-92 cluster, which downregulates THBS1 expression." (PMID 25165708, 2014). "The suppression of THBS1 facilitates an angiogenic phenotype, contributing to the aggressive nature of angiosarcoma." (PMID 39594601, 2024). "Reduced expression of thrombospondin-1 (THBS1) has been reported in MYC-amplified angiosarcomas (more on MYC amplifications in angiosarcomas below), and its expression is either downregulated or lost across many cancers." (PMID 25374893, 2013). "Also, upregulation of miR-17-92 decreased thrombospondin-1 (THBS1) expression that enhanced angiogenesis, indicating a MYC-miR-17-92 dependent pathogenesis in the MYC-amplified hemangiosarcoma tumor tissues." (PMID 26137468, 2015). "Interestingly, members of the miR17-92 cluster target THBS1 directly, demonstrating one mechanism by which MYC amplification may induce an aberrant angiogenic phenotype in angiosarcomas." (PMID 25374893, 2013).
Atrophy (5 papers, 2021 to 2025). Any weakening or degeneration, especially through lack of use. "Remarkably, Thbs1−/− mice showed significantly less loss of heart weight and body weight with 48 h of fasting compared with matched controls, which again suggests that induction of Thbs1 is likely involved in cardiac atrophy." (PMID 34168130, 2021). "Thbs1 (Thrombospondin-1) has been certified that its overexpression can lead to lethal cardiac atrophy." (PMID 36312255, 2022). "THBS1 induced lethal cardiac atrophy and played a vital role in intermittent hypoxia-induced fibroblast activation and cardiac fibrosis when overexpressed." (PMID 36212039, 2022). "Thbs1 has been demonstrated to induce lethal heart atrophy through PERK-ATF4-regulated autophagy, and so mu opioid receptor agonism may have a role in the regulation of autophagy in HT22 cells." (PMID 36699066, 2022). "We next investigated the molecular basis for Thbs1-mediated cardiac atrophy." (PMID 34168130, 2021). "Mechanistically, Thbs1 binds and activates the endoplasmic reticulum stress effector PERK, inducing its downstream transcription factor ATF4 and causing lethal autophagy-mediated cardiac atrophy." (PMID 34168130, 2021). "Here we crossed Thbs1 DTG mice into the Atf6−/− genetic background, which did not reduce the atrophy associated with the Thbs1 DTG, nor did it extend viability." (PMID 34168130, 2021). "In addition, these same mice displayed less fasting-induced cardiac atrophy, together suggesting a role for Thbs1 in regulating adult cardiomyocyte size and ventricular plasticity." (PMID 34168130, 2021). "Finally, deletion of Thbs1 in mice protects from cardiac atrophy." (PMID 34168130, 2021). "Here we show that Thbs1, but not Thbs2, Thbs3 or Thbs4, induces lethal cardiac atrophy when overexpressed." (PMID 34168130, 2021). "Taken together, these results indicate that Thbs1-mediated cardiac atrophy and premature lethality are independent of CD36 or CD47." (PMID 34168130, 2021). "Deletion of Thbs1 effectors/receptors, including ATF6α, CD36 or CD47 does not diminish Thbs1-dependent cardiac atrophy." (PMID 34168130, 2021).
ischemia (5 papers, 2008 to 2023). A hypoperfusion of the BLOOD through an organ or tissue caused by a PATHOLOGIC CONSTRICTION or obstruction of its BLOOD VESSELS, or an absence of BLOOD CIRCULATION. "Excessive matricellular glycoprotein thrombospondin 1 (TSP1) levels in circulation have been found to play an important role in ischemia-reperfusion injuries of different organs, by acutely suppressing vasorelaxation and chronically remodeling vascular bed." (PMID 34698263, 2021).
keloid (5 papers, 2007 to 2025). An irregularly shaped, elevated mark on the skin caused by deposits of excessive amounts of collagen during wound healing. "Overproduction of ECM, including fibronectin-1 and thrombospondin-1, is a hallmark of keloid fibroblasts." (PMID 41465196, 2025). "LSKL is a peptide that is a selective antagonist of thrombospondin-1 (TSP-1), a key activator of latent TGF-β, which is heavily implicated in fibrotic processes like hypertrophic scars and keloids." (PMID 41424791, 2025). "In addition to normal fibroblasts, we investigated the effect of BioD on the expression of fibronectin-1 and thrombospondin-1 in keloid-derived fibroblasts (kFB)." (PMID 41465196, 2025). "It has been reported that THBS1 may modulate keloid formation through up-regulation of the matrix plasminogen/plasmin system." (PMID 27574659, 2015). "Multi-omics investigations, including proteomics, have identified abundant levels of collagens (I and III), FN1, THBS1, and TGFB1 in keloids compared to normal skin." (PMID 41465196, 2025). "We validated the expression of ECM-2, ESM1, THBS1, FBLN5 and COL18A1 in keloids, incisional scars and adhesions and the analysis indicated an elevated expression of ECM2, THBS1 and FBLN5 in keloid/incisional scars and COL18 in peritoneal adhesions as compared to leiomyomas." (PMID 17718906, 2007).
metabolic syndrome (5 papers, 2020 to 2024). A cluster of metabolic risk factors for CARDIOVASCULAR DISEASES and TYPE 2 DIABETES MELLITUS. "Rodent metabolic syndrome models recapitulate these findings, as evidenced by increased circulating THBS1 levels observed in DIO mice." (PMID 38954467, 2024).
Myocardial fibrosis (5 papers, 2015 to 2025). "For example, THBS1 promotes myocardial fibrosis by activating the TGF-β signalling pathway, whereas STAT3 affects cardiomyocyte proliferation and apoptosis by regulating cytokine signalling." (PMID 40427439, 2025). "miR-17-92 cluster (miR-17, miR-18a, miR-19a, and miR-19b), also target CTGF as well as thrombospondin-1 in the context of myocardial fibrosis." (PMID 26404540, 2015). "In addition, Thbs1 is a physiological regulator of TGFβ activation and is involved in the regulation of the myocardial fibrosis–related ceRNA network." (PMID 35211156, 2022). "THBS1, a multifunctional extracellular matrix protein, promotes myocardial fibrosis by activating TGF-β signalling and reducing microvessel density, and exacerbates myocardial fibrosis by inhibiting angiogenesis, e.g., by blocking VEGF and NO signalling." (PMID 40427439, 2025).
osteoarthritis (5 papers, 2015 to 2025). A noninflammatory degenerative joint disease occurring chiefly in older persons, characterized by degeneration of the articular cartilage, hypertrophy of bone at the margins and changes in the synovial membrane. "To further investigate the role of THBS1 in the progression of osteoarthritis, we constructed an adeno-associated virus that overexpresses THBS1." (PMID 40475787, 2025). "THBS1 is expressed in cartilage tissue and its expression is decreased in the tissues of patients with advanced osteoarthritis." (PMID 40475787, 2025). "To elucidate the specific mechanism by which THBS1 delays osteoarthritis and the reasons for its differential expression under mechanical stress, we constructed an in vitro mechanical stress stimulation model using mouse chondrocytes." (PMID 40475787, 2025). "Some researchers have also found a potential role for THBS1 in the treatment of osteoarthritis." (PMID 40475787, 2025). "In this study we plan to analyze the role of THBS1 in the progression of osteoarthritis." (PMID 40475787, 2025). "And several studies have also shown that THBS1 may be related to cartilage degeneration in osteoarthritis." (PMID 40475787, 2025). "Furthermore, THBS1 effectively slows the progression of osteoarthritis and protects articular cartilage." (PMID 40475787, 2025). "Marie Maumus and colleagues reported that THBS1 secreted by adipose-derived MSCs may play a protective role in a collagen-induced osteoarthritis (CIOA) mouse model by chondroprotective effects and anti-inflammatory effects on T lymphocytes." (PMID 35371051, 2022). "Notably, our previous research indicated that THBS1 overexpression alleviated surgery-induced osteoarthritis; however, after GPX4 knockout in chondrocytes, THBS1 was unable to effectively reduce osteophyte formation, cartilage loss was exacerbated, and cartilage damage severity increased." (PMID 40475787, 2025). "Among differentially secreted proteins induced in coculture, we identified thrombospondin-1 (THBS1) as a potential candidate involved in the chondroprotective effect of ASCs and explored its function both in vitro and in vivo in the collagenase-induced osteoarthritis (CIOA) model." (PMID 29238343, 2017). "Inhibitors of WNT (DKK3 and FRZB), and antagonists of BMP/TGFβ (CD109, CHRDL2, DCN FMOD, INHBA and THBS1) signalling were decreased or absent in the aged inner region, consistent with the reported upregulation of these pathways in IDD and its closely related condition osteoarthritis." (PMID 33382035, 2020).
periodontitis (5 papers, 2021 to 2025). An acute or chronic inflammatory process that affects the tissues that surround and support the teeth. "In vitro mechanistic studies show that miR-671-5p inhibits hPDLFs inflammatory responses and promotes cell viability and migration by targeting THBS1, providing new insights into the pathogenesis of periodontitis." (PMID 40999501, 2025). "circLRRC4C and miR-485-3p were co-regulators of the THBS1 level, while this axis functioned in tandem to regulate periodontitis progression." (PMID 40220480, 2025). "This research confirmed the specific interaction between THBS1 and miR-485-3p, revealing a significant upregulation of THBS1 in both periodontitis tissues and cells." (PMID 40220480, 2025). ",20 circLRRC4C/miR-485-3p/THBS1 axis expression profiles and mechanisms were validated in periodontitis tissues and cells induced by LPS." (PMID 40220480, 2025). "As part of this study, the authors examined the effects of the circLRRC4C/miR-485-3p/THBS1 axis on periodontitis, with the goal of providing a clinical reference for preventing and managing periodontitis." (PMID 40220480, 2025). "The study concluded that silencing circLRRC4C alleviated LPS-induced PDLC injury by targeting the miR-485-3p/THBS1 axis and was therefore useful for future diagnosis and treatment of periodontitis." (PMID 40220480, 2025). "Analysis of clinical samples revealed that THBS1 levels in GCF were significantly higher in periodontitis patients than in healthy controls (P < 0.001)." (PMID 40999501, 2025). "Five mRNAs, i,e., FOS, JUN, KLF2, WIF1, and THBS1, for further validation via RT-qPCR on 15 periodontitis and 15 healthy gingivae samples." (PMID 36045361, 2022). "Thrombospondin 1 is elevated in gingival tissues with periodontitis and this overexpression is induced by lipopolysaccharide from Porphyromonas gingivalis (a keystone pathogen) via innate immunity system activation and inflammatory responses." (PMID 34065604, 2021). "Inhibition of THBS1 effectively improved LPS-induced periodontitis." (PMID 40220480, 2025). "However, the potential interactions among circLRRC4C, miR-485-3p, and THBS1, and their implications for periodontitis remain to be elucidated." (PMID 40220480, 2025). "Applying such approaches could unravel broader regulatory networks governing miR-671-5p/THBS1 axis functions in pathogenesis of periodontitis." (PMID 40999501, 2025). "CircLRRC4C induces periodontitis progression by adsorbing miR-485-3p-mediated THBS1 expression." (PMID 40220480, 2025). "Subsequently, the authors examined whether THBS1 was regulated by miR-485-3p in the periodontitis model." (PMID 40220480, 2025). "The authors hypothesized that circLRRC4C might exacerbate periodontitis progression by modulating the miR-485-3p/THBS1 axis." (PMID 40220480, 2025). "Notably, a recent periodontitis study found that circLRRC4C upregulates THBS1 expression by sponging miR-485-3p." (PMID 40999501, 2025). "JUN, FOS, KLF2, THBS1 and WIF1 were identified as key regulator in periodontitis and validated to be highly expressed in IPT through RT-qPCR." (PMID 36045361, 2022). "PRKCQ-AS1, has not been studied in periodontitis, and our analysis showed that PRKCQ-AS1 may act as sponge of miR-141, miR-6512, miR-513c, and regulate the expression of CXCL1, PTGS2 (COX-2), THBS1 and PRKCQ." (PMID 36045361, 2022).